RN7SL151P (RNA, 7SL, cytoplasmic 151, pseudogene)
Gene: Miscellaneous RNA gene on chromosome 9 (21,699,314 to 21,699,596, forward strand). Ensembl gene ENSG00000244230.
Homologues: Orthologues: chimpanzee Metazoa_SRP (99% identical). Paralogues in human: RN7SL1 (81% identical), RN7SL2 (80% identical), RN7SL3 (80% identical), RN7SL5P (79% identical), RN7SL296P (78% identical), RN7SL357P (77% identical), RN7SL18P (76% identical), RN7SL566P (76% identical), RN7SL589P (76% identical), RN7SL814P (76% identical), RN7SL218P (76% identical), RN7SL60P (76% identical), and 706 more.
Diseases named in the same sentence as RN7SL151P in open-access papers:
RN7SL151P is named in the same sentence as 1 disease in open-access papers, as found by Europe PMC text mining. Sharing a sentence is not in itself a finding about the gene and the disease.
RN7SL151P shares sentences with these, for which no sentence is quoted: lymph node metastasis (1 paper).